MAPT (microtubule associated protein tau)
Diseases named in the same sentence as MAPT in open-access papers (continued):
Sharing a sentence is not in itself a finding about the gene and the disease.
Parkinson disease (continued). "These multivariate ASD associations mapped to genes, including MAPT and NSF which are known to involved in biological pathways linked to neural disorders such as infantile epilepsy and Parkinson’s Disease." (PMID 39696186, 2024). "We have previously illustrated the capacity of SVAs to influence gene expressions within Parkinson’s disease, highlighting the role of SVA_67 to modulate genes at the MAPT locus within the PPMI cohort and a CRISPR deletion model." (PMID 38540776, 2024). "Neurodegenerative disorders associated with MAPT mutations are bvFTD, primary progressive aphasia, progressive supranuclear palsy, corticobasal degeneration, and the FTD-parkinsonism and FTD-ALS clinical complexes." (PMID 37730935, 2024). "Several mutations in MAPT, linked to FTD with parkinsonism, were also found to increase tau oligomer formation." (PMID 39161653, 2024). "Based on linkage analyses conducted in the 1990s, patients with mutations in the MAPT gene and tau deposits in neuronal and glial cells were classified as having FTD and parkinsonism linked to chromosome 17q21 (FTDP-17)." (PMID 39199184, 2024). "MAPT p.R406W has been reported in several familial cases of FTD with parkinsonism, all with early onset." (PMID 39606324, 2024). "Recent studies have shown a genotype–phenotype correlation of MAPT haplotypes in Parkinson’s disease (PD) wherein certain haplotypes (such haplotype H1) are linked to particular cognitive domains, including memory and visuospatial function." (PMID 38136993, 2023). "Peripheral B cells were immunophenotyped in 41 early Parkinson’s disease patients and 41 age-, gender- and MAPT genotype-matched controls." (PMID 36993946, 2023). "A subset of variants in MAPT—encoding the microtubule-associated protein tau and the causative gene for chromosome 17-linked familial FTD with parkinsonism —have been found in cases of early-onset dementia resembling clinical AD." (PMID 35393555, 2022). "CK2 is involved in the phosphorylation and aggregation of other pathological proteins like microtubule associated protein tau (MAPT) and α-syn, proteins involved in Alzheimer’s (AD) and Parkinson’s disease (PD)." (PMID 35659303, 2022). "Common genetic variance in apolipoprotein E (APOE), β-glucocerebrosidase (GBA), microtubule-associated protein tau (MAPT), and α-synuclein (SNCA) has been linked to cognitive decline in Parkinson’s disease (PD), although studies have yielded mixed esults." (PMID 35106798, 2022). "While we identified ASE sites within MAPT, we also identified four sites of ASE in KANSL1, suggesting that the high Parkinson’s disease risk H1 allele is associated with lower KANSL1 expression, consistent with our functional assessment." (PMID 36074904, 2022). "More recently, the association between progranulin mutations and parkinsonism enabled us to distinguish between FTDP-17 (MAPT) and FTDP-17 (PGRN)." (PMID 34943897, 2021). "It is well documented that the P301L MAPT mutation and C9orf72 repeat expansion were are predominantly associated with FTD in the western population, often accompanied by Parkinsonism." (PMID 34305575, 2021). "Parkinsonism with rigidity and akinesia is commonly seen in bvFTD,82 in sporadic FTD and especially in FTD arising from mutations in MAPT, GRN and C9orf72." (PMID 34458729, 2021). "Since that time, over 60 MAPT mutations have been identified, usually causing behavioral variant FTD and/or parkinsonism clinically." (PMID 31870644, 2020). "Apart from these two common genetic associations (MAPT and PGRN), parkinsonism in familial FTD can also be liked with chromosome 9 open reading frame 72 (C9orf72) gene where overlap with motor neuron disease (FTD-MND) is commonly seen." (PMID 33250855, 2020). "Parkinsonism associated with familial FTD and MAPT mutation varies from mild to the aggressive form in severity and can occur early or late in this spectrum." (PMID 33250855, 2020).
Parkinson disease (continued). "These included microtubule-related MAP2 and MAPT, as well as WNT3 and MICB, all implicated in the pathogenesis of diseases such as Parkinson’s, Alzheimer’s and schizophrenia." (PMID 31504236, 2019). "Of note, higher rates of a family history of dementia and/or parkinsonism were noted in the EOPSP group when compared with the LOPSP group, even when we discount the two identified MAPT mutation EOPSP cases." (PMID 31299107, 2019). "The MAPT H1 haplotype has been identified as a predictor of cognitive decline in Parkinson's disease (PD)." (PMID 29899731, 2018). "We assessed possible RBD (pRBD) status using the RBD screening questionnaire and investigated known susceptibility variants for Parkinson’s disease located in the α-synuclein (SNCA) and tau (MAPT) gene loci in 325 Parkinson’s disease patients." (PMID 29466944, 2018). "They localize to distal enhancer of ESR1 and MAPT genes, which are related to osteoporosis or Parkinson's disease, respectively." (PMID 29669022, 2018). "Neurofibrillary lesions consisting of insoluble Tau (MAPT) filaments form in brains from patients with Alzheimer's, Parkinson's, Pick's disease and in Purkinje cell degeneration and ALS." (PMID 30135644, 2018). "The microtubule-associated protein tau (MAPT) region has been conceptualized as a model of the interaction between genetics and functional disease outcomes in neurodegenerative disorders, such as Parkinson disease (PD)." (PMID 27147968, 2016). "Furthermore, rs199533 (in MAPT), which is the strongest association (P = 6.7 × 10−16) within the region of significant SNPs in our GWAS meta-analysis, has been previously reported as being associated with Parkinson’s disease, as have been various other SNPs in this region." (PMID 27466229, 2016). "By contrast, in our cohorts, we observed a significant positive correlation between MAPT H2 haplotype and global parkinsonism." (PMID 27458716, 2016). "The MAPT gene on chromosome 17, encoding the tau protein, was the first gene identified in families with FTD and parkinsonism." (PMID 26388768, 2015). "Genetic studies have identified several genes associated with monogenic FTD: in 1998, mutations in the microtubule-associated protein tau (MAPT) gene on chromosome 17 were identified in families with FTD and parkinsonism." (PMID 26388768, 2015). "Evidence points toward a possible interplay between the microtubule-associated protein tau (MAPT) and α-synuclein in the pathology of sporadic Parkinson's disease (PD)." (PMID 25505609, 2014). "The human tau gene is segregated to a rare form of familial FTD with Parkinsonism linked to chromosome 17 (FTDP-17), demonstrating MAPT as a causative gene of neurodegenerative disorders." (PMID 24808823, 2014). "Prior to the discovery of the genetic forms of disease, i.e. mutations of MAPT and SNCA, toxin-based rodent models characterized in vivo parkinsonism research." (PMID 25352339, 2014). "For example, APP interacts with susceptibility genes to type 2 diabetes (LAMA1 and IDE) and genes associated with Parkinson's disease risk including SNCA and MAPT." (PMID 24376773, 2013). "Several implicated host proteins—notably HTRA1, MAPT, and RAB6A—are highly expressed in the cerebellum and basal ganglia, aligning with observed clinical features such as ataxia, opsoclonus‐myoclonus, and parkinsonism." (PMID 40259581, 2025). "The MAPT P301L mutation is one of the most common variants associated with FTD worldwide, leading to behavioral disturbances, aphasia, cognitive impairment, and parkinsonism." (PMID 40219788, 2025). "The aberrant methylation of the MAPT gene may contribute to Parkinson’s disease by altering axonal cytoskeleton integrity." (PMID 38239489, 2023). "MAPT, C9orf72 and progranulin (GRN) variants are common genetic causes of familial FTD and may also cause parkinsonism." (PMID 37746582, 2023). "Presentation with rest tremor should not exclude FTD-parkinsonism due to MAPT variant as a differential diagnosis." (PMID 37746582, 2023).
Parkinson disease (continued). "MAPT mutations are the only known genetic aetiologies of FTLD-Tau, which may cause variable cognitive (executive and verbal), behavioural and motor (e.g. parkinsonism) deficits." (PMID 36707904, 2023). "This hypermethylation lowers MAPT expression, which may explain, at least in part, why women have a reduced incidence of Parkinson’s disease compared to men." (PMID 38239489, 2023). "The study found that 30 studies provided evidence of a relationship between genetics, gene mutations, age, and Parkinson's disease, with 12 studies specifically finding that genetic mutations in SNCA, LRRK2, PARK2, PINK1, DJ1, GBA, and MAPT alleles are associated with the disease." (PMID 36909056, 2023). "It is demonstrated that inherited Frontotemporal Dementia (FTD) and parkinsonism, with extensive filamentous tau deposits in the brain in the absence of Aβ deposits, are caused by mutations in the MAPT, the microtubule associated protein tau gene." (PMID 36014310, 2022). "Along these lines, MAPT was found to be a causal protein for multiple psychiatric disorders and Parkinson’s disease but not for AD, which is classically associated with abnormal MAPT accumulation." (PMID 35882878, 2022). "According to the information from 88 GGT patients worldwide, the most common phenotypes for GGT are PPA (25%) and bvFTD (22.7%), less common ones include upper motor neuron disorders, amnesia, Richardson syndrome, parkinsonism and CBS, similar to phenotype composition in GGT with MAPT mutations." (PMID 35392986, 2022). "While our data do not exclude a possible association between the MAPT gene and Parkinson’s disease, they provide strong evidence that KANSL1 plays a crucial role in the disease." (PMID 36074904, 2022). "Parkinsonism is found in approximately 20–30% of patients in FTLD; in particular, it is frequently observed in familial FTD, with mutations linked to microtubule associated protein Tau (MAPT), progranulin (GRN or PGRN), and chromosome 9 open reading frame 72 (C9ORF72) repeat expansion." (PMID 33800495, 2021). "To further elucidate the influence of APOE and MAPT variability on dementia in Parkinson's disease, we genotyped postmortem brain tissue samples of clinically and pathologically well-characterized Parkinson's donors and performed a survival analysis of time to dementia." (PMID 33613437, 2021). "The H1 haplotype of the microtubule-associated protein tau (MAPT) gene is a common genetic risk factor for some neurodegenerative diseases such as progressive supranuclear palsy, corticobasal degeneration, and Parkinson’s disease." (PMID 34532319, 2021). "In this context, the MAPT haplotype, either H1 or H2, of donors and stem cell lines could also play an important role since the H1 MAPT haplotype is associated with a higher risk for developing PSP, CBD, AD, and Parkinson’s disease (PD)." (PMID 34858989, 2021). "Four MAPT H1 subhaplotypes, but not the H2 haplotype, were significantly associated with specific clinical features in Parkinson’s disease." (PMID 32767721, 2020). "For instance, the MAPT pathway is involved in the aetiopathogenesis of Alzheimer’s disease (AD), Parkinson’s disease (PD), parkinsonism, and amyotrophic lateral sclerosis (ALS); GRN in AD, PD, parkinsonism, motor neuron disease (MND); and C9orf72 in ALS, AD, and parkinsonism." (PMID 31405128, 2019). "Although we observed increased global parkinsonism, bradykinesia and gait disturbance scores with decreasing MAPT gene total expression, the association between them was not significant." (PMID 27458716, 2016). "Since the literature suggests that altered levels or ratios of MAPT RNA isoforms play a role in the susceptibility of age-related neurodegenerative diseases associated with motor impairment, we also analysed the relationship between isoform levels to parkinsonism and MAPT haplotypes." (PMID 27458716, 2016).
Parkinson disease (continued). "Recently, we have shown that the Parkinson’s disease (PD) susceptibility locus MAPT (microtubule associated protein tau) is associated with parkinsonism in older adults without a clinical diagnosis of PD." (PMID 27458716, 2016). "Background. α-Synuclein (SNCA) and microtubule-associated protein tau (MAPT) are the two major genes independently, but not jointly, associated with susceptibility for Parkinson's disease (PD)." (PMID 25960998, 2015). "Another ALS phenotype, FTD and Parkinson's disease (FTDP), was discovered in North America and was linked to chromosome 17, showing clinical heterogeneity as in all cases in which mutations in the microtubule-associated protein tau gene (MAPT) located on chromosome 17q21 were described." (PMID 25157374, 2014). "For example, significant eQTLs that mapped to the Parkinson disease associated gene, MAPT were only detected in post-mortem brains but not in blood." (PMID 24303001, 2013). "Moreover, in addition to the genes mapped to the sequentially numbered PARK1-15 loci, other genes, such as MAPT, ATXN2, ATXN3, spatacsin, and POLG1, are known to cause syndromes that can clinically manifest with parkinsonism as one of the symptoms." (PMID 22623900, 2012). "The main goal of this work was to describe two MJD patients displaying the parkinsonian triad (tremor, bradykinesia and rigidity), namely on what concerns genetic variation in Parkinson's disease (PD) associated loci (PARK2, LRRK2, PINK1, DJ-1, SNCA, MAPT, APOE, and mtDNA tRNAGln T4336C)." (PMID 22023810, 2011). "In fact, several studies have now demonstrated that genetic variation in the critical 5' and promoter region of the MAPT locus was associated with typical late-onset PD (LOPD) and irregular tau accumulation has been observed in both parkinsonism kindreds and sporadic LOPD cases." (PMID 16930453, 2006). "Neurofibrillary tangles, a prominent neuronal accumulation of hyperphosphorylated and filamentous forms of the microtubule associated protein tau, are found in FTD with Parkinsonism linked to chromosome 17, the hereditary variant of FTD, caused by mutations in the tau gene." (PMID 15550170, 2004). "It is well known that the toxic amyloid-like aggregates of β-amyloid (APP), tau (MAPT), α-synuclein (SNCA or PARK1), and islet amyloid polypeptide (IAPP) are linked with neurodegeneration in Alzheimer’s disease (AD), frontotemporal dementia (FTD), Parkinson’s disease (PD) or Type 2 diabetes (T2D)." (PMID 35565658, 2022). "The microtubule-associated protein Tau encoding gene MAPT, which was also identified as a key-age-related PI gene, is strongly associated with neurodegeneration and related diseases including Alzheimer's and Parkinson's diseases and also associated with bone-mineral density." (PMID 36267464, 2022). "Microtubule-associated protein tau (MAPT) gene mutations are the most prevalent cause of familial frontotemporal dementia (fFTD), a condition linked to mutations on chromosome 17 (p.A152T), which has also been implicated in AD and Parkinson's disease with dementia." (PMID 34122554, 2021). "Finally, mutations in the microtubule-associated protein tau (MAPT) gene could cause a spectrum of phenotypes which include ALS, Parkinsonism, and cognitive impairment." (PMID 24068985, 2013). "This study reveals significant hypomethylation in the MAPT and SNCA genes in peripheral blood leukocytes of Mexican Mestizo patients with Parkinson’s disease." (PMID 40703677, 2025). "In studies using brain tissue, MAPT DNA methylation patterns have been variable and region-specific as investigated in PSP, AD and Parkinson’s Disease." (PMID 39975316, 2025). "However, prominent Parkinsonism has not been reported previously for the P301L MAPT mutation." (PMID 34305575, 2021).
Parkinson disease (continued). "Our result suggests that rs8070723 G allele might influence MAPT expression level by reducing the binding affinity of upstream regulatory protein PBX1, therefore providing a mechanistic association with neurodegenerative diseases including Progressive Supranuclear Palsy and Parkinson’s Disease." (PMID 31001319, 2019). "We also identified a strong negative relationship between the allele predisposing to left-handedness at rs199512, which is an eQTL of MAPT and MAPT-AS1, and a diagnosis of Parkinson’s disease for the mother of the UK Biobank participants." (PMID 31504236, 2019). "In 1994, Wilhelmsen and colleagues reported linkage of an autosomal dominantly inherited form of FTD with parkinsonism and amyotrophy (disinhibition-dementia-parkinsonism-amyotrophy complex, DDPAC) to chromosome 17q21.2, the region that contains the MAPT gene." (PMID 26751493, 2016). "We sought to define how the early cognitive deficits in newly diagnosed patients with Parkinson’s disease map onto changes in brain activation, and how these activations in patients varied as a function of the common genetic variations in COMT, MAPT and APOE." (PMID 25080285, 2014). "After obtaining the findings outlined earlier in the article, we screened exon 7 of the MAPT gene in 114 PSP, 8 CBD, and 48 idiopathic Parkinson's disease cases from the QSBB archival collection." (PMID 22595371, 2012). "Indeed, regions with high MAPT expression also demonstrated a strong level of connectivity (hubs), which predicted network perturbation within PSP patients as well as those with Parkinson's disease." (PMID 37086932, 2023). "When we compared the Z-scores obtained from these two TWAS, we found that 12 genes discovered in International Parkinson Disease Genomics Consortium (IPDGC) cohort (e.g., MAPT, SNCA, ATG14, DVL3, and MTOR) could be replicated." (PMID 30824768, 2019). "Besides being major contributors of neurodegeneration process, APP, CREB1, HSP90AA1, MAPT and PTEN have varying degree of interactions with many known Parkinson's disease genes (see CSPNW)." (PMID 24688734, 2013). "In MAPT mutation carriers, ALS tends to be a late manifestation in patients already afflicted with parkinsonism, rather than a separate entity." (PMID 23338750, 2013). "Other genes at non-PARK loci (MAPT, SCA1, SCA2, spatacsin, POLG1) cause syndromes with parkinsonism as one of the symptoms." (PMID 22623900, 2012). "These include those loci traditionally noted as “Parkinson loci” as well as others that are not, including MAPT, SCA2, SCA3, and spastacsin, which can clinically present as Parkinson disease but often is clinically distinct." (PMID 20955928, 2010). "Genetic studies have suggested that Parkinson's disease patients with LRRK2 mutations are more likely to exhibit the PIGD phenotype, while those who are homozygous for the H1 haplotype of the microtubule-associated protein tau (MAPT) gene tend to present with a non-tremor-dominant phenotype." (PMID 40401020, 2025). "We also reported rare heterozygous variants in neurodegenerative disease related genes, including TRPM7, MAPT, and APP that could be associated with parkinsonism phenotypes; however, none have been previously reported as pathogenic." (PMID 39867380, 2025). "The association with the MAPT (H1c clade) and RPSA-MOBP loci may suggest common genetic pleiotropy across FTD and progressive supranuclear palsy (PSP) (MAPT and RPSA-MOBP loci) and across FTD, AD, Parkinson disease (PD), and cortico-basal degeneration (CBD) (MAPT locus)." (PMID 38889728, 2024).